FOXP3 (forkhead box P3)
Diseases named in the same sentence as FOXP3 in open-access papers (continued):
Sharing a sentence is not in itself a finding about the gene and the disease.
breast carcinoma (continued). "This would also at least partly explain why FoxP3+ Tregs seem to promote tumor-progression in some cancers, such as colorectal cancer, while inhibiting tumor growth in other cancer types, such as breast cancer." (PMID 34051744, 2021). "A reduced CD8+/FOXP3+ ratio has been associated with aggressive non-luminal tumors in breast cancer." (PMID 32954467, 2021). "This study not only provides preclinical evidence supporting the application of ADQ in inhibiting breast cancer metastasis but also sheds novel insights into TAM/CXCL1/NF-κB/FOXP3 signaling as a promising therapeutic target for Treg modulation and breast cancer immunotherapy." (PMID 34461944, 2021). "Previous work showed that intratumoral γδ T cell numbers were positively correlated with advanced tumor stages, HER2 expression status, FOXP3+ cells, and high lymph node metastasis, but inversely correlated with relapse-free survival and overall survival of breast cancer patients." (PMID 34381711, 2021). "We used FOXP3-Tet-off MCF7 cells to evaluate whether FOXP3 affects ATF3 protein expression since MCF7 (human breast cancer) cells express very small amounts of FOXP3." (PMID 34768829, 2021). "Interestingly, analysis of IL-17RB expression in lymph node metastasis and matched tumors of breast cancer patients confirmed that IL-17RB is increased in lymph nodes and correlates with FOXP3 frequency." (PMID 34632244, 2021). "Thus, a higher dose of calycosin led to a reduction of migration and invasion of human breast cancer cells, by targeting Foxp3-mediated VEGF and MMP-9 expression." (PMID 34462889, 2021). "Taken together, our findings systematically confirmed that FOXP3 could inhibit breast cancer metastasis by regulating MTA1 expression, providing an experimental basis and new ideas for the treatment of metastatic breast cancer." (PMID 34307133, 2021). "Moreover, clinical trials showed the efficacy of chemotherapy in reducing the frequency of CD4+CD25+FoxP3+ Tregs and their suppressive function in the circulation of patients with hepatocellular carcinoma and in tumor tissues of breast cancer patients." (PMID 33532902, 2021). "Such a favorable role of immunosuppressive Foxp3+ T cell depletion was demonstrated previously in a mouse model of mammary carcinoma where reduced immunosuppressive activity significantly affected tumor progression through increased cancer cell death and improved overall survival." (PMID 34440813, 2021). "Therefore, in this study, when we analysed clinical breast cancer samples, we defined samples with only nuclear staining as positive for FOXP3." (PMID 34307133, 2021). "Furthermore, STAT3-mediated IDO1 expression was found to be upregulated in breast cancer cell-induced MDSCs, which suppressed effector T cells and hyperactivated the infiltration of the Foxp3+ Tregs in TME." (PMID 33957948, 2021). "This study intended to explore a new mechanism by which FOXP3 inhibits breast cancer metastasis." (PMID 34307133, 2021). "Furthermore, Ladoire and colleagues found the association of both high CD8+ and low FOXP3+ lymphocyte infiltrates following NAC was linked with improved RFS and OS in a cohort that included all breast cancer subtypes." (PMID 34135901, 2021). "In addition, as a determinant of the prognostic value of cytotoxic TILs in breast cancer, the ratio of total FoxP3+ Tregs to CD8+ CTLs can be taken into account." (PMID 34885122, 2021). "Notably, MDSCs-produced IDO1 favors Foxp3 + Tregs and tumor-induced immunosuppression, which in turn leads to advanced breast cancer clinical stage." (PMID 33957948, 2021). "In vitro and in vivo experiments were used to determine whether the regulation of MTA1 by FOXP3 affected the invasion and migration of breast cancer cells." (PMID 34307133, 2021). "In addition, Studies have shown that, during primary systemic chemotherapy (PSC), a low number of FOXP3-positive TR cell was related to favorable therapeutic outcomes in breast cancer." (PMID 34367945, 2021).
breast carcinoma (continued). "In short, FOXP3 may stand in the most crucial list of biomarkers for breast cancer, bringing compelling results in terms of treatment and management of the disease." (PMID 34938323, 2021). "There are still many downstream molecules associated with breast cancer metastasis in the FOXP3 regulatory network that have not yet been discovered and studied." (PMID 34307133, 2021). "Studies of mice with reduced expression of the transcription factor FOXP3, which leads to breast cancer with lung metastases in females, provided further evidence for exosome-mediated release of miR-200 members from tumor cells and their utility as markers of metastasis." (PMID 34884985, 2021). "Importantly, FOXP3’s regulation of MTA1 affected the ability of breast cancer cells to invade and metastasize in vitro and in vivo." (PMID 34307133, 2021). "Furthermore, FoxP3 can act both as a tumor suppressor as seen in breast cancer but also enables cancer cells to prevent T-cell responses directed towards them and hence results in tumor progression and poor prognosis." (PMID 34900746, 2021). "Adding to the same observation, the significant downregulation of FOXP3 also resulted in the reduced survival in breast cancer FOXP3 has been reported to modulate the expression of various genes involved in the process of carcinogenesis to exert its suppressing role in tumor development." (PMID 34938323, 2021). "In our study transcription factor, FOXP3 promoter methylation and expression were studied and analyzed in breast cancer patients of the northern region of India using methylation-specific PCR, real-time PCR, and immunohistochemistry to assess its role as a potential biomarker." (PMID 34938323, 2021). "While a high infiltration of FoxP3+ Tregs at the tumor site correlates with an impaired overall survival in patients with melanomas, cervical-, renal- and breast cancers an opposite effect was observed in colorectal, head and neck as well as esophageal cancers." (PMID 34332614, 2021). "Meanwhile, lymphocytes regulatory network consisting of FoxP3+ and Ki67+ T cells could be found in the invasive margin of breast cancer." (PMID 34631551, 2021). "Moreover, the high expression of FOXP3 serves as a good predictor of the survival of patients in breast cancer, prostate cancer, and gastric cancer." (PMID 34938323, 2021). "Therefore, we investigated the effects of different ICIs on tumor-infiltrating FoxP3+ Tregs in breast cancer patients." (PMID 32616706, 2020). "In breast cancer, estrogen receptor induces Meis1 and Forkhead box P3 (Foxp3) upregulation." (PMID 33402862, 2020). "Thus, treatment or prevention of tumor progression in HR-positive breast cancer would have to be focused on FOXP3+ regulatory T cells." (PMID 32216826, 2020). "FOXP3 expression has been reported in several tumors such as melanoma, pancreatic cancer, breast cancer and lung cancer (and is referred to as cancer-FOXP3) despite its non-redundant role in the regulation of Treg cell differentiation, development and functions." (PMID 32425930, 2020). "Indeed, tumor-infiltrated FoxP3+ Th17 cells have been detected in several types of tumors, including breast cancer, melanoma, and colon cancers, and are regarded as immune suppressors." (PMID 32604872, 2020). "Our findings indicate the clinical significance and prognostic value of FOXP3, PD-1/PD-L1 checkpoint and TILs in metaplastic breast cancer and confirm that a subset of metaplastics may benefit from immune-based therapies." (PMID 32939056, 2020). "Furthermore, FOXP3 is involved in immune escape mechanisms and both poor survival and improved survival in breast cancer have been reported." (PMID 32222891, 2020). "In addition, a decreased ratio of CD8 + TILs to FOXP3 + Tregs infiltrating and surrounding tumors correlated with poor prognosis in breast cancer." (PMID 32222891, 2020).
breast carcinoma (continued). "In HR-positive breast cancers, despite the fact that FOXP3+ TIL was significantly higher in DCIS-INV than in pure DCIS, the other TIL subsets seemed to increase in number at a late stage of DCIS progression, or seemed unlikely to be associated with in situ to invasive transition." (PMID 32216826, 2020). "We investigated the effect of breast cancer cells on the expression level of ICs on Tregs (defined as CD4+CD25+FoxP3+Helios+), in addition to the effect of anti-PD-1, anti-PD-L1 or both mAbs on the expression of ICs on Tregs in the presence of breast cancer cells." (PMID 31614877, 2019). "Breast cancer accumulates Foxp3+ Treg cells upon tumor progression, and we have demonstrated that transient ablation of Treg cells in established, highly immuno-suppressive breast tumors results in a significant increase in anti-tumor immunity in primary and metastatic tumors." (PMID 31555258, 2019). "Thus, tumor infiltrating pDCs from human breast cancer patients display enhanced tryptophan metabolism and are capable of inducing more FoxP3+ T cells." (PMID 31440253, 2019). "FOXP3 is a transcription marker expressed in a vast majority of breast cancer-infiltrating Tregs." (PMID 31016433, 2019). "In this study, the immunohistochemical results showed that in breast cancer patients, high CCL20 expression and increased FOXP3+ TILs infiltrates were both associated with high histological grade, axillary lymph node metastases, positive HER2, and high Ki67 index." (PMID 31852159, 2019). "While IL-10 stimulates immunosuppressive FOXP3 expressing T regulatory (Treg) cells, its role in breast cancer remains unclear, as it has been reported to both promote and inhibit breast cancer growth." (PMID 30640711, 2019). "The results suggest that CCL20 and FOXP3+ TILs may have synergistic effects, and their upregulated expressions may lead to immune evasion in breast cancer." (PMID 31852159, 2019). "Combinatorial immunotherapeutic approaches aiming at blocking CCL20 and depleting FOXP3 might improve therapeutic efficacy in breast cancer patients." (PMID 31852159, 2019). "In addition, a significant correlation was observed between CCL20 expression and FOXP3+ TILs infiltration in breast cancer tissue (rs = 0.359, P < .001)." (PMID 31852159, 2019). "Interestingly, our qPCR data demonstrate a significantly negative correlation between expression of Sdc-1 and IL-4 (r = - 0.564, P = 0.028), IL-17 (r = - 0.571, P = 0.026), and Foxp3 (r = - 0.607, P = 0.016) in breast carcinoma tissues of IBC patients." (PMID 31145753, 2019). "Moreover, CD8+FoxP3+ T cells were induced in vitro in co-cultures with breast cancer and ovarian cancer cell lines, whereas in the presence of non-cancerous cells this subset was not induced." (PMID 30755279, 2019). "A relatively high number of FoxP3+ Treg cells, resulting in a decreased CD8+/FoxP3+ ratio, is also significantly associated with shorter overall survival in the majority of solid tumors investigated, including breast cancer." (PMID 31164094, 2019). "In breast cancer, the prognostic significance of FOXP3+ Tregs is widely varied." (PMID 31852159, 2019). "In addition, significant correlation between CCL20 expression and FOXP3+ TILs infiltration in breast cancer tissue was identified (rs = 0.359, P < .001)." (PMID 31852159, 2019). "However, in our study the full-length FOXP3 transcript can be detected in breast cancer cells and nuclear FOXP3 is expressed in some breast cancer samples." (PMID 29549328, 2018). "Furthermore, functional studies revealed that blocking the FOXP3/Gal-1 interaction restores the tumor-suppressive properties of FOXP3 in breast cancer cells." (PMID 29549328, 2018). "Furthermore, we examined FOXP3 expression, in human primary breast cancer tissues, from 165 breast cancer patients." (PMID 29549328, 2018). "Taken together, these results indicate that FOXP3 suppresses VEGF expression in breast cancer." (PMID 29970908, 2018).
breast carcinoma (continued). "Additionally, we investigated the prognostic value of changes in the levels of CD8+ TILs and FOXP3+ TILs in each breast cancer subtype." (PMID 30233820, 2018). "Moreover, the forkhead box protein 3 (FOXP3) plays an important role in the generation of regulatory T cells (Treg), but the precise role, function, and prognostic abilities of FOXP3 in breast cancer have yet to be established." (PMID 30285668, 2018). "Our findings not only identify a novel function of nuclear Gal-1 in breast cancer, but also suggest that blocking the Gal-1-FOXP3 interaction might be a promising treatment for wild-type FOXP3-positive breast cancer." (PMID 29549328, 2018). "It is reported that FOXP3 is usually mutant, absent, or cytoplasmic distribution in breast cancer cells, which increases the risk of breast cancer." (PMID 29549328, 2018). "To test this hypothesis we overexpressed FOXP3 (or GFP control) in the breast cancer cell line BT549 and transfected these and wild- type (WT) cell lines with either miR-155 or miR-control." (PMID 29963231, 2018). "Moreover, FOXP3 plays an important role in breast cancer metastasis, by regulating the expression of CXCR4 and SATB112,13." (PMID 29549328, 2018). "However, on the contrary, an observation from a cancer study indicated that sclareol reduced the number of splenic CD4+, CD25+, FoxP3+, and Treg cells in breast cancer mice." (PMID 29751535, 2018). "Collectively, these results suggest that the expression of Gal-1 in FOXP3-positive breast cancer cells may dampen the tumor-suppressive properties of FOXP3 by interacting with the FKH domain of FOXP3." (PMID 29549328, 2018). "We found that the full-length FOXP3 transcript was detected in 6 breast cancer cases (6/11, 54.5%)." (PMID 29549328, 2018). "Therefore, an important question is how the tumor-suppressive function of FOXP3 is negated during the development of breast cancer." (PMID 29549328, 2018). "Moreover, by analyzing single-cell RNA-sequencing data from primary breast cancer cells, we found that the full-length FOXP3 transcript was present in 54.5% of breast cancer samples." (PMID 29549328, 2018). "A potential limitation of T-cell co-stimulation by current immune checkpoint inhibitors is a tumor milieu enriched with TGFβ, which strongly correlated with FOXP3 expression in our analysis of The Cancer Genome Atlas (TCGA) data set of diverse human cancers, including melanoma and breast cancer." (PMID 29467463, 2018). "This analysis demonstrated that nuclear FOXP3 was expressed in 32.1% of breast cancer samples." (PMID 29549328, 2018). "We found CCL1, CCL22, and FoxP3 expressing cells in most breast cancer tissues analyzed." (PMID 30572845, 2018). "Primary goal of our study was to evaluate the prognostic value of CD3, CD8, and FOXP3 mRNA expressions, as markers for T‐cell infiltration, in early‐stage breast cancer patients treated with anthracycline‐based adjuvant chemotherapy in the context of two prospective phase III randomized trials." (PMID 30240146, 2018). "There is ample evidence that a pCR in the primary breast cancer following NAC is significantly associated with high levels of tumour infiltration by TILs, CD4+ and CD8+ T effector cells, CD56+ NK cells and high CD8+: FOXP3+ T cell ratios." (PMID 29390966, 2018). "Taken together, these results not only confirmed that the DNA-binding FKH domain of FOXP3 is required for binding Gal-1, but also suggested that the DNA-binding ability of FOXP3 might be abolished by its interaction with Gal-1 in the breast cancer cells." (PMID 29549328, 2018). "In addition, expression of vascular endothelial growth factor (VEGF) was downregulated by FOXP3 in breast cancer cell lines." (PMID 29970908, 2018). "We then investigated the effect of FOXP3-expressing breast cancer cells on angiogenesis in vitro." (PMID 29970908, 2018). "Importantly, our data showed that UBC9 (both mRNA and proteins) are up-regulated by FOXP3 in human MCF7 breast cancer cells." (PMID 30011797, 2018).
breast carcinoma (continued). "However, in our previous study and the present one31, the expression of nuclear FOXP3 via immunohistochemistry was observed in a substantial number of breast cancer samples." (PMID 29549328, 2018). "We found that Gal-1 is a novel interacting protein of FOXP3 in breast cancer." (PMID 29549328, 2018). "Bos and colleagues utilized Foxp3–DTR mice given mammary tumors." (PMID 30294332, 2018). "Bohling and Allison found density of intratumoral FOXP3+ Tregs was significantly associated with high histological grade, larger size and ER negative status in breast cancer." (PMID 28029650, 2017). "Data have suggested that FOXP3 expression in tumor cells could be a poor prognostic factor in breast cancer, colorectal cancer, and bladder cancer, indicating FOXP3 significantly contributed to tumor progression." (PMID 28903735, 2017). "In this retrospective analysis including 98 breast cancer patients treated with anti-Her-2 therapy, we studied potential relationship between TILs infiltration, count of FOXP3+ Tregs, CD68+ Mφ and IL-17+ Th17 in both intratumoral and stromal site with patients’ survival." (PMID 28029650, 2017). "Interestingly, FOXP3 expression in breast cancer cells was correlated with high Ki-67 index, indicating high proliferative activity of FOXP3-positive tumors." (PMID 28923073, 2017). "In addition, in TCGA datasets, tumor samples of patients with breast cancer were divided into two subgroups (FOXP3low and FOXP3high) by a medium value of FOXP3 expression." (PMID 28562349, 2017). "Similarly, we observed the prevalence of CD8+CD25+FOXP3+ T cells in the peripheral circulation of patients with advanced breast cancer, in comparison to age-sex matched healthy donors." (PMID 28487507, 2017). "In this study, it was found that FOXP3 regulates miR-7 and miR-155 in breast cancer cell lines, suggesting that aberrant expression of miRNAs may be an important influence of FOXP3-deficency in primary tumor cells." (PMID 27999212, 2017). "In conclusion, the retrospective study including 98 breast cancer patients treated with anti-Her-2 therapy revealed that tumor TILs as well as its FOXP3+, CD68+ phenotypes in stromal site, and expression of FOXP3 in cancer cells were significantly associated with OS." (PMID 28029650, 2017). "In our breast cancer models, the increased frequency of Gr-1+CD115+CCR2highCX3CR1lowmonocytes in the lungs of tumor-bearing mice was associated with an increased presence of CD25+Foxp3+Treg." (PMID 28744322, 2017). "However, HR breast cancer is the only breast cancer subtype where FOXP3+ infiltrate predicts a worse survival." (PMID 27777769, 2016). "FOXP3+ TILs level is a promising prognostic factor in breast cancer." (PMID 27566250, 2016). "However, the research on the prognostic significance of tumor-infiltrating FOXP3+ Tregs in breast cancer is still limited and the results are controversial." (PMID 27566250, 2016). "The subsets of T cells (CD4+, CD8+, FOXP3+(forkhead box protein 3), and PD-1+(programmed death molecule 1)) infiltrating breast cancer, however, can have different pathobiological significance and prognostic characteristics and are a matter of continuing debate." (PMID 27777963, 2016). "The result implied that ER+ breast cancer was accompanied with lower FOXP3+ TILs." (PMID 27566250, 2016). "Several studies showed that higher FOXP3+ Tregs indicated poor prognosis in patients with breast cancer while some revealed no direct association between them." (PMID 27566250, 2016). "Moreover, high tumor Foxp3 levels in tumor cells are also found to be related to better outcome of cancer patients of gastric cancer and Her2-positive breast carcinoma." (PMID 27457382, 2016). "Likewise, we demonstrate that upregulation of Foxp3 expression in mammary tumor cells reduces Rspo3 gene expression." (PMID 26735887, 2016).